INSR (insulin receptor)
Diseases named in the same sentence as INSR in open-access papers (continued):
Sharing a sentence is not in itself a finding about the gene and the disease.
tumor (289 papers, 2009 to 2026). "Genes that were decreased in expression across all tumor types were associated with the insulin receptor signaling and ion channel transport among other pathways." (PMID 36909536, 2023). "In terms of patient outcome, higher tumour INSR expression, and IGF1R expression, was associated significantly with shorter overall survival." (PMID 34554347, 2022). "Our finding that higher tumour INSR expression is associated with shorter overall patient survival concurs with a report that membranous insulin receptor is associated with shorter tumour-specific survival." (PMID 34554347, 2022). "For NODM patients, insulin use or high insulin receptor expression in tumor cells is associated with higher malignancy rates in pancreatic precursor lesions." (PMID 35252207, 2022). "The insulin-like growth factors (IGFs), IGF-1 and IGF-II, which bind to the IGF receptor type 1 (IGF-1R) and the insulin receptor (IR), have been implicated in the growth, survival, and metastasis of tumor cells." (PMID 35399718, 2022). "The up‐regulated expression of INSR is a marker of tumour‐associated endothelial cells and is functionally involved in angiogenesis." (PMID 35184398, 2022). "The most interesting finding of the current study was that the major isoform of INSR in the tumour vasculature is the proliferation associated isoform INSR-A and not the metabolic isoform INSR-B." (PMID 30559346, 2019). "Insulin receptor expression in tumor cells (EIR) tended to be associated with dMMR in UICC stage II CRC: EIR negative patients tended to exhibit dMMR less frequently (16.8%) than patients with EIR positive CRCs (83.2%; P = 0.089)." (PMID 30680065, 2018). "Some studies have suggested functional association between mRNA expression of insulin receptor-related and insulin-like growth factor receptors and tumor cells." (PMID 28095793, 2017). "The only association observed between body constitution and tumor markers was between height and InsR expression." (PMID 28030849, 2017). "Together, these data indicate that Grb10 modulates Ras signaling in untransformed cells as well as tumor cells, and that loss of Grb10 in untransformed cells increases the magnitude and duration of Ras effector activation despite reduced insulin receptor levels." (PMID 26000738, 2015). "Given the role of the INSR in glucose metabolism, we postulate that the change of IR-A/IR-B mRNA ratio in tissues could be associated with differences in metabolism in tumor tissue compared to normal tissue." (PMID 24571613, 2014). "Also, diabetic patients may have alterations in hepatocyte expression of surface receptors such as insulin receptor or insulin-like growth factor receptor that increase susceptibility to unidentified tumor promoting factors." (PMID 23317091, 2013). "In PDAC, autocrine insulin-like growth factor-1 (IGF-1) and paracrine insulin stimulate the IGF-1 receptor (IGF1R) and insulin receptor (IR) to increase tumor growth and glycolysis." (PMID 40630951, 2025). "IGF2 is overexpressed in tumor cells and myofibroblasts, where it activates the insulin receptor (IR) and IGF1 receptor (IGF1R), promoting cellular survival and proliferation." (PMID 41465387, 2025). "Linsitinib (OSI-906) is one of these inhibitors, and it targets the tyrosine kinase domain of both IGF-1R and insulin-receptor (IR), preventing tumor cell proliferation and inducing apoptosis." (PMID 39596005, 2024). "For instance, a study using a genomic screen of the tumour vasculature showed the involvement of INSR in tumour angiogenesis." (PMID 38874510, 2024). "The primary mechanism underlying the reliance of metformin on insulin involves reduction in insulin levels, which leads to diminished insulin binding to the insulin receptor (IR), thereby impeding tumor growth." (PMID 37835462, 2023). "The growth promoting factors Myc, Imp, and Insulin receptor in the tumor cells are important for tumor expansion and killing of the host." (PMID 37549261, 2023).
tumor (continued). "This has provided insights on tumor growth strategies, like the involvement of Myc, Imp, and the insulin receptor pathway." (PMID 37549261, 2023). "The tumor-promoting effects of Ins are mainly mediated by the Insulin Receptor (IR), a receptor tyrosine kinase (RTK) expressed in almost 80% of BCs and associated with worse prognostic outcomes." (PMID 37461077, 2023). "lnc-INSR suppresses the immune microenvironment by regulating the differentiation of Treg cells, thereby promoting tumor growth." (PMID 37808187, 2023). "As an example, the tumor endothelium can be classified into four distinct subclusters also enabling the annotation of INSR as PCa tip cell marker and Fibulin5 and ENPP2 as PCa artery specific markers." (PMID 35717322, 2022). "Consistent with relatively high tumour INSR expression, insulin receptor was detected readily in seven of eight cell lines, at lower levels in MKN74 and in metastatic cells." (PMID 34554347, 2022). "Insulin can combine with the insulin receptor on the surface of tumor cells to promote the mitosis of tumor cells." (PMID 36199796, 2022). "We found that the INSR+ tumour endothelial cells were more enriched in the SSNs than in the normal tissues, illustrating the remodelling of endothelial cell subtypes in the TME." (PMID 35184398, 2022). "Higher tumour cell insulin receptor concentration and availability should allow cells to achieve higher receptor occupancy and hence increased responsivity to insulin." (PMID 34554347, 2022). "In accordance with this, IGF1R and INSR act as oncogenes in PCa, enhancing tumor growth, proliferation, invasion, and angiogenesis." (PMID 35454907, 2022). "A low-carbohydrate diet also suppresses prostate cancer tumor growth in mice compared to a Western diet, which increases serum insulin, blood glucose, and tumor tissue insulin receptor levels." (PMID 35745105, 2022). "Overexpression of INSR is correlated with a poor prognosis for oncology patients and can be used as an early tumor-related marker." (PMID 35216085, 2022). "The anabolic and anti-apoptotic actions of insulin promote tumor development in hyperinsulinemic subjects through binding of insulin to the insulin receptor (IR), the insulin like growth factor-insulin receptor (IGF-IR) or a hybrid receptor (IR-IGF-IR)." (PMID 34535145, 2021). "We identify overexpression of stearoyl-coenzyme desaturase (SCD1) as a molecular signature of HFHS tumors that largely predicts the tumor sensitivity to insulin by increasing insulin receptor (IR) expression and tumor growth." (PMID 34162829, 2021). "Increased INSR expression in tumor cells is also modulated by the upregulation of Sp1 and HMGA1 transcription factors." (PMID 33673232, 2021). "Indirect effects are likely mediated by systemic reductions in insulin, which results in decreased tumor-specific activation of the insulin receptor (IR) and suppression of mitogenic PI3K and Ras signaling." (PMID 34103538, 2021). "Because of its function within the PI3K pathway, increased insulin is likely to stimulate insulin receptor (IR)-rich tumours promptly activating downstream signalling and tumour maintenance." (PMID 33810522, 2021). "DDR1 was critical for IGF-IR endocytosis and trafficking into early endosomes, and DDR1 overexpression induced upregulation of both the IGF1 receptor (IGF1R) and the insulin receptor (IR) in normal and tumor cells." (PMID 34206590, 2021). "Lnc-INSR was found to regulate the differentiation of Treg cells to inhibit the immune microenvironment and thereby promote tumor growth." (PMID 33173530, 2020). "The compensatory mechanism within the InsR/IGF signaling network was widely described in different tumor types." (PMID 33604294, 2020). "In an independent deep sequencing study for identification of embryo-specific genes that become re-expressed in tumour endothelial cells, INSR was also found to be a specific marker of the tumour vasculature." (PMID 30559346, 2019).
tumor (continued). "ROS1, which belongs to one subfamily of kinase insulin receptor genes, is a proto‐oncogene, highly expressed in a variety of tumour cells." (PMID 31001929, 2019). "This seems to be applicable to the IR-expressing tumor samples of our collective: first, the insulin receptor’s proliferative stimuli are known to be conveyed via RAS signaling, especially via its mitogenic isoform IR-A." (PMID 30989432, 2019). "In a genomic screen for determinants of the tumour vasculature we identified insulin receptor to mark the tumour endothelium." (PMID 30559346, 2019). "Additional (pre-)clinical evidence on the importance of INSR in tumour angiogenesis was provided by the demonstration that anti-angiogenic treatment reduces vascular INSR expression." (PMID 30559346, 2019). "In a genomic screen for determinants of the tumour vasculature, we identified insulin receptor (INSR) to mark the tumour endothelium." (PMID 30559346, 2019). "The anti-InsR antibody against phosphorylated Tyr1185 in the beta chain of the InsR molecule showed strong or medium positivity in the same tumor tissues in which at least 50% of maximal density was detected by the phospho-array." (PMID 31616636, 2019). "Our results on intervention in the insulin/INSR signalling axis by siRNA and antibody-mediated targeting in vitro and in vivo demonstrate the capacity of this pathway to regulate tumour angiogenesis." (PMID 30559346, 2019). "Insulin can stimulate tumor cell survival and proliferation by signaling through the insulin receptor (IR)." (PMID 31315653, 2019). "In the tumor of the patient described in this work, other embryonic pathways were upregulated, and it is possible that the tumor cells switched to other signaling to overcome INSR blockade." (PMID 31480400, 2019). "Immunohistochemical staining for INSR in CRC tissue confirmed the overexpression in the tumour vasculature, as compared to vessels in normal tissues, where INSR expression was very low or absent." (PMID 30559346, 2019). "Thirdly, anti-angiogenic treatment of tumours was shown to suppress the expression of vascular INSR." (PMID 30559346, 2019). "Fetal isoforms of the insulin receptor have been described in tumor cells, binding both insulin and IGF-II with high affinity." (PMID 31207998, 2019). "The overexpression of INSR in tumour vessels was further assessed and quantified in a series of 11 different tumour types." (PMID 30559346, 2019). "For these reasons we investigated the role of INSR in the biology of EC and in the formation of (tumour) vessels." (PMID 30559346, 2019). "While INSR is steeply upregulated in tumours as compared to normal kidney, two cycles of treatment with sunitinib significantly repressed the expression of INSR by up to 8-fold." (PMID 30559346, 2019). "This overexpression of INSR suggests a function in the process of tumour angiogenesis, and points to a relationship with tumour aggressiveness and prognosis." (PMID 30559346, 2019). "Gene array analysis of HCC tumour tissue from xenograft mice given IP ascorbate (4.0 g/kg/3 days) identified changes in the transcript levels of 192 genes/ncRNAs involved in insulin receptor signalling, metabolism and mitochondrial respiration." (PMID 31754384, 2019). "HSF-1 is able to associate with cell cycle regulators and modulate the metabolism of glucose and lipids by indirectly regulating insulin receptor protein expression, which has been demonstrated to be important for tumor initiation and development." (PMID 29348836, 2017). "A combined nuclear InsR/ER expression score for each tumor was therefore calculated resulting in four different groups: InsR−/ER+ (n = 609), InsR+/ER+ (n = 182), InsR+/ER− (n = 32), and InsR−/ER− (n = 76)." (PMID 29234306, 2017). "We then assessed the correlation of these mRNA levels with tumor stage, activation of the INSR/IGF1R receptors (indicating activation of the IGF pathway) and the antiproliferative efficacy of an inhibitor of IGF1R tyrosine kinase." (PMID 28882129, 2017).
tumor (continued). "INSR was substantially down-regulated in the tumor samples (median = 0.58; range = 0.01–471.75; RQ < 1 in 84.2% of cases), as was IGFBP-3 (median = 0.52; range = 0.05–2.96; RQ < 1 in 80.7% of cases)." (PMID 28545426, 2017). "Tumor promoting activity of insulin can be mediated by insulin receptor (INSR) as well as cross-activation of the insulin-like growth factor 1 receptor (IGF1R) family, resulting in activation of downstream signaling cascades." (PMID 28038446, 2017). "The IGF-1R/InsR signaling as an anti-tumor target has accordingly been studied in preclinical NSCLC models using either small molecule inhibitors towards the kinase domain or IGF-1R/InsR targeting antibodies." (PMID 27384680, 2016). "Based on the results from a recent window-of-opportunity study, serum insulin, tumour insulin receptor expression, p-Akt, and Ki-67 are potential biomarkers of tumour metformin sensitivity." (PMID 27903276, 2016). "In fact, a compensatory activation of insulin receptor-AKT signaling has been previously reported with IGF-1R monoclonal antibody therapy in human tumor cells." (PMID 26317790, 2015). "Conversely, expressing a constitutively active isoform of the Insulin Receptor in Ras/Src-activated cells (InR/Ras/Src) was sufficient to elevate Wg signaling, promoting tumor overgrowth in animals fed a control diet." (PMID 26573956, 2015). "Targeting IGF-1R/IR (insulin receptor) signaling with BMS-754807 has also resulted in cell growth inhibition in several pediatric tumor types, in vitro and in vivo." (PMID 25748921, 2015). "This allows for not only targeting of IGF-1R but also the INSR isoform, insulin receptor A (INSR-A), which can mediate tumor growth." (PMID 26217584, 2015). "PC3 cells have been previously established in a CAM assay, so we investigated the effects of changes in IGF1R/INSR levels on tumor growth and vessel density using PC3 PCa cells." (PMID 24809298, 2014). "Transfections for transient IGF1R/INSR overexpression or downregulation were performed once prior placing the tumor cells on the CAM." (PMID 24809298, 2014). "It has been well documented that down-regulation of IGF-1R or insulin receptor inhibits cell proliferation, metastasis and in vivo tumor growth." (PMID 24970814, 2014). "Mitogenic signaling by INSR has been described in some tumor models and examples have been provided in which the IGF1R or INSR compensates for the inhibition of the opposite receptor." (PMID 24434591, 2014). "This pathway is downstream of several growth factor receptors such as insulin receptor and insulin like growth factor I receptor, which coordinate tumor growth." (PMID 24858012, 2014). "Inhibition of AKT upregulated the tumor levels of P-InsR/IGF-IR, InsR, P-HER3, HER3, P-HER2, HER2, the FGFR substrate P-FRS2 and FGFR2 proteins." (PMID 23844554, 2013). "Studies have identified transcription factors and cofactors that regulate expression of insulin receptor in tumour cells." (PMID 23983688, 2013). "There is evidence that the mitogenic response to insulin is more pronounced after activation of isoform A of the insulin receptor, which is overexpressed in some tumour cells, than after activation of isoform B of the receptor." (PMID 23983688, 2013). "Further, treatment with AZD5363 for one to three days also increased tumor levels of InsR, IGF-IR and FGFR 1-4 mRNAs." (PMID 23844554, 2013). "In normal cells and several tumor types, insulin receptor (IR) and insulin-like growth factor (IGF) receptor activation are examples of growth factor signaling pathways that transduce effects on cell metabolism, growth and survival, as reviewed previously." (PMID 22680924, 2012). "IGF-1R and insulin receptor interaction has been seen in many human tumor cell lines after the appearance of IGF-1R monoclonal antibodies." (PMID 21729319, 2011).
tumor (continued). "We calculated the proportion of IR-A relative to total insulin receptor composition (IR-A + IR-B) in matched tumor and normal pairs as determined by a 2(−ΔCt) calculation." (PMID 22046260, 2011). "Tumorigenicity assays in nude mice indicated that tumor growth induced by CREB3 knockdown could be partly rescued by decreased INSR expression or enhanced RBM38 expression." (PMID 38952575, 2024). "The targeting ligands can identify a variety of representative tumor biomarkers, such as FR, TfR, insulin receptor (IR), estrogen receptor α (ERα), prostate-specific membrane antigen (PSMA), mucin-1 (MUC1), nucleolin, and human epidermal growth factor receptor 2 (HER2)." (PMID 39204392, 2024). "The impairment or attenuation of miRNAs could potentially stabilize RFLNB and INSR expression, promoting tumor growth." (PMID 38673800, 2024). "Here we show that the insulin-INSR axis drives OC cell proliferation and influences response to platinum, supporting the idea that overexpression of INSR could drive tumor progression." (PMID 39622796, 2024). "Similarly, another study also identified two types of tumor ECs: INSR+ tumor EC (INSRhiHSPG2+PLVAP+) and ACKR1+ tumor EC (ACKR1+SELP+IL1R1+) in early-stage lung cancer that radiologically manifests as part-solid nodules." (PMID 37187731, 2023). "Furthermore, since FOLR regulates the PI3K pathway through INSR, and acts as a bridge between tumor metabolic reprogramming and EMT, dual targeting of FOLR and INSR can monitor the occurrence, metastasis and prognosis of CRC with greater accuracy." (PMID 37475862, 2023). "IRS proteins play a key role in tumor metabolism by regulating signaling of INSR." (PMID 36245982, 2022). "Except for fibroblasts, a total of 937 endothelial cells were also obtained, which were subclustered into five subsets, including extra-alveolar capillary ECs (Endo-C1; EDN1+), tumor ECs (Endo-C3; INSR+), and other ECs (Endo-C2, ICAM1+; Endo-C4, MAP1B+; Endo-C5, CXCR4+)." (PMID 36046337, 2022). "One question that arises from inhibiting IGF1R in our tumor models is whether there may be compensatory expression or activation of the insulin receptor (INSR)." (PMID 36568144, 2022). "There was some indication that reduced promoter methylation might contribute to higher tumour INSR expression." (PMID 34554347, 2022). "INSR expression was higher in tumour than in normal gastric tissue." (PMID 34554347, 2022). "Tumor endothelial cells were mainly represented by clusters 2 and 4, and showed high expression of angiogenesis markers such as VWA1 and HSPG2, as well as INSR, encoding an endothelial marker protein and possible therapeutic target (arrowheads)." (PMID 34663877, 2021). "Furthermore, InsR expression was visible in the cytoplasm of tumor cells indicating InsR activation by the insulin/IGF axis." (PMID 34202040, 2021). "Furthermore, the clinical relevance of these observations was supported by detecting a coexpression of cytoplasmic InsR (characteristic for its activation) and PD-L1 in tumor tissues from PDAC patients." (PMID 34202040, 2021). "However, recent clinical trial results have proved disappointing, with IGF1R-targeted approaches activating the insulin receptor to promote tumor growth." (PMID 33723215, 2021). "Since we hypothesized that phosphorylation of IGF‐1R would be predictive for tamoxifen resistance, we only selected tumor samples harboring IGF‐1R expression to evaluate the p‐IGF‐1R/InsR scoring." (PMID 31490549, 2020). "Additionally, analysis of publicly available clinical PCa tumor data showed metastatic prostate tumors demonstrate a positive correlation between insulin receptor expression and the EMT transcription factor FOXC2." (PMID 31379747, 2019). "The strong overexpression of INSR (mainly INSR-A) in the tumour vasculature and its functional role in activation signals suggests that this signalling axis may serve as a target for therapy." (PMID 30559346, 2019).